PCK2 (phosphoenolpyruvate carboxykinase 2, mitochondrial)
Description:
Mitochondrial phosphoenolpyruvate carboxykinase that catalyzes the conversion of oxaloacetate (OAA) to phosphoenolpyruvate (PEP), the rate-limiting step in the metabolic pathway that produces glucose from lactate and other precursors derived from the citric acid cycle. Can play an active role in glyceroneogenesis and gluconeogenesis. Also acts as a serine/threonine-protein kinase: phosphorylates and activates ACSL4, thereby promoting ferroptosis.
Synonyms: PEPCK-M; mtPCK2; PEPCK2; PEPCK
Tractability: PROTAC: ubiquitination databases record sites on it; its protein half-life has been measured.
Target class: Enzyme; Lyase
Gene: Protein-coding gene on chromosome 14 (24,094,053 to 24,110,598, forward strand). Ensembl gene ENSG00000100889.
Subcellular location: Mitochondrion
Subcellular location (Human Protein Atlas): Mitochondria
Pathways (Reactome):
Metabolism: Gluconeogenesis
Gene Ontology:
Molecular function: manganese ion binding; phosphoenolpyruvate carboxykinase (GTP) activity; protein binding; protein serine/threonine kinase activity; phosphoenolpyruvate carboxykinase activity; GTP binding; purine nucleotide binding
Biological process: positive regulation of ferroptosis; cellular response to dexamethasone stimulus; cellular response to glucose stimulus; cellular response to insulin stimulus; gluconeogenesis; glycerol-3-phosphate biosynthetic process; hepatocyte differentiation; oxaloacetate metabolic process; response to starvation; cellular response to tumor necrosis factor; positive regulation of insulin secretion; pyruvate biosynthetic process; response to dexamethasone; response to lipopolysaccharide
Cellular component: mitochondrion; mitochondrial matrix
Genetic constraint (gnomAD): Loss-of-function variants: 56 observed, 66.21 expected, observed/expected ratio (o/e) 0.85, 90% interval 0.68 to 1.06. The upper end of that interval is the gene's LOEUF score, 1.06, which puts it in group 4 of 6, group 1 being the genes least tolerant of losing a copy. Missense variants: 843 observed, 890.24 expected, observed/expected ratio (o/e) 0.95, 90% interval 0.89 to 1. Synonymous variants: 305 observed, 325.93 expected, observed/expected ratio (o/e) 0.94, 90% interval 0.85 to 1.03.
Homologues: Orthologues: chimpanzee PCK2 (99% identical), rabbit PCK2 (95% identical), pig PCK2 (95% identical), guinea pig PCK2 (94% identical), macaque PCK2 (94% identical), dog PCK2 (94% identical), mouse Pck2 (92% identical), rat Pck2 (92% identical), tropical clawed frog pck2 (74% identical), zebrafish pck2 (66% identical), Drosophila melanogaster Pepck2 (63% identical), Drosophila melanogaster Pepck1 (62% identical), and 3 more. Paralogues in human: PCK1 (69% identical).
Diseases named in the same sentence as PCK2 in open-access papers:
PCK2 is named in the same sentence as 124 diseases in open-access papers, as found by Europe PMC text mining. Sharing a sentence is not in itself a finding about the gene and the disease. The quoted sentences say what the papers report.
Hyperglycemia (80 papers, 2010 to 2026). An increased concentration of glucose in the blood. "Several glycolytic or gluconeogenic genes, including Pck2, Gpi1, and Pfkm, were also diminished, possibly contributing to the heightened glycogen stores and hyperglycemia persisting in RYGB HFD relative to RYGB Chow." (PMID 41598416, 2026). "Concurrently, PSP suppresses hepatic glucose overproduction by transcriptionally downregulating gluconeogenesis-related genes, particularly Pck2 (phosphoenolpyruvate carboxykinase), thereby mitigating hyperglycemia." (PMID 40458823, 2025).
Insulin resistance (78 papers, 2006 to 2025). Increased resistance towards insulin, that is, diminished effectiveness of insulin in reducing blood glucose levels. "These three miRNAs regulate genes associated with pancreatic cancer (Bcra2) and insulin resistance (Pck2 and Trib3) and regulate the expression levels of genes (Rela and Fos) among shared pathways." (PMID 39022651, 2024). "The WB results suggested that VT improved insulin resistance, inhibited gluconeogenesis through the Akt/Foxo1/Pck2 signaling pathway, and reduced fatty acid synthesis via the SREBP1c/Fasn signaling pathways." (PMID 31096578, 2019). "Among these pathways, PPARGC1A, CD36, IRS2, PCK2, and IGF1 were enriched in the AMPK signaling pathway, and PCK2 was additionally enriched in the adipocytokine signaling pathway and insulin resistance." (PMID 37958518, 2023).
diabetes (59 papers, 2004 to 2025). "PCK1 and PCK2 have been proposed as potential diabetes and obesity-associated genes." (PMID 36360783, 2022). "Notably, we found that the anti-diabetes drug metformin could rescue bone loss and craniofacial malformation caused by Pck2 ablation via AMPK signaling, thereby indicating a novel strategy to treat bone metabolic dysfunction." (PMID 36376276, 2022). "It has been found that an increase in the activity of Pck2 leads to exacerbation of diabetes mellitus by increasing glucose production." (PMID 40387487, 2025). "In line with the array data, a marked downregulation in the majority of lipogenesis- and diabetes-related genes (Pck2, Gck and Ins) as well as in cytokines was observed in BPF-treated livers compared to both CAF and SC groups." (PMID 39061835, 2024). "Our results show significant overexpression of PCK2 in Langerhans islets of rats with long-term diabetes." (PMID 34203686, 2021). "To determine, whether long-term type 2 diabetes mellitus affects PCK2 within Langerhans islets, the measurement of the proteomic level of PCK2 was done." (PMID 34203686, 2021). "Thus, our LCM-cap-IA integration was applied to study the impact of diabetes on the expression of PCK2 within the Langerhans islet." (PMID 34203686, 2021). "Based on this evidence, the role of PCK2 in the pathophysiology of diabetes could be suggested." (PMID 34203686, 2021). "From these findings, it can be concluded that PCK2 is up-regulated in Langerhans islets of T2D rats, which, together with information from the literature, suggests its role as an important regulatory factor of cellular metabolism involved in various pathological conditions, also including diabetes." (PMID 34203686, 2021). "Interestingly, most transcripts namely, Pck2, Prkab2, Pik3r1, Foxo1, Irs1 and Pik3r5 are commonly involved in these pathways and this suggests a significant involvement and contribution of these genes in aberrant skeletal muscle metabolism during diabetes." (PMID 34190986, 2021). "Based on text mining, most of the highly common diabetes-related genes in the literature were correlated with glucagon and AMPK signaling pathways such as HNF4A, PCK2, and SIRT1, which were among the most interactive genes in the PPI analysis." (PMID 36360783, 2022). "Although the role of PEPCK-C (cytoplasmic form; PCK1) has been thoroughly investigated in diabetes and obesity 38, that of its counterpart isozyme, PEPCK-M (mitochondrial form, PCK2), remains unexplored." (PMID 35982907, 2022). "As expected, other genes (PCK2, DOC2B) pointed at insulin regulation, diabetes and obesity." (PMID 33510859, 2021).
hepatoma (31 papers, 2004 to 2025). "PCK2 has been implicated in immune regulation, proliferation, and metastasis of hepatocellular carcinoma, and is emerging as a novel predictive biomarker and metabolic-related clinical target." (PMID 38890507, 2024). "The non-synonymous somatic variant in PCK2 was identified in hepatocellular carcinoma tissue, suggesting that PCK2 was associated with hepatocellular carcinoma." (PMID 34650006, 2021). "IGF2BP3 K76la upregulates PCK2 expression in lenvatinib-resistant hepatocellular carcinoma cells, triggering serine metabolism reprogramming and conferring drug resistance." (PMID 40994548, 2025). "In our investigation, a number of bioinformatics datasets, including TCGA, CPTAC, and HPA, were utilized to prove the discrepancies in the expression of PCK2 in hepatocellular carcinoma tissues and normal adjacent tissues at different levels." (PMID 38890507, 2024). "In public datasets, patients with lower PCK2 expression in the primary tumor of colorectal cancer or hepatocellular carcinoma were more likely to develop distant metastasis." (PMID 38720107, 2024). "Some human cancers have been reported to have a high level of PCK2 expression, but it is in hepatocellular carcinoma that PCK2 expression is down-regulated, and low PCK2 expression is likely connected with a bad prognosis in HCC patients." (PMID 38890507, 2024). "In conclusion, overexpression of PCK2 inhibits the biological functions of hepatoma cell proliferation, invasion and migration." (PMID 38890507, 2024). "It was demonstrated that PCK2 was involved in the tumor proliferation of lung cancer, prostate cancer, and hepatocellular carcinoma." (PMID 35265226, 2022). "Therefore, the in-depth study of PCK2 in hepatocellular carcinoma will provide a new scientific basis and possibility for the treatment and prognosis of hepatocellular carcinoma." (PMID 38890507, 2024). "Upon lactification, Insulin-like Growth Factor 2 mRNA-Binding Protein 3 (IGF2BP3) stabilizes both PCK2 and NRF2 mRNA, augments the activity of the antioxidant system, and bolsters the resistance of hepatocellular carcinoma (HCC) to lenvatinib." (PMID 41179284, 2025). "This study reveals that in lenvatinib‐resistant hepatocellular carcinoma, increased glycolysis results in lactate accumulation and lysine lactylation of IGF2BP3, which increase the expression of PCK2 and NRF2." (PMID 39450426, 2024). "Elevated expression of the upstream gluconeogenesis enzyme PCK2 has been noted in many tumor types include colon cancer, NSCLC and hepatocellular carcinoma." (PMID 39193344, 2024). "Recent studies have reported upregulation and/or increased phosphorylation of PCK1 or PCK2 in different human malignancies, including colon cancer, non-small cell lung cancer (NSCLC), melanoma, and lymphoma, as well as metastatic breast cancer and hepatocellular carcinoma (HCC)." (PMID 34620839, 2021).
type 2 diabetes (28 papers, 2013 to 2023). "The cT1-increasing allele in rs111723834 (missense variant in PCK2, also an intronic variant in NRL) was associated with lower aminotransferases, lower risk of type 2 diabetes, and lower triglycerides." (PMID 32247823, 2020).
lung carcinoma (24 papers, 2015 to 2025). "Previous studies demonstrated that knockdown or inhibition of PCK2 in low glucose or glucose deprivation conditions results in mitochondrial-associated apoptotic cell death in lung cancer." (PMID 40182032, 2025). "PCK2 also is associated with lung cancer by promoting tumorigenesis through its gluconeogenic function." (PMID 34650006, 2021). "Inhibition and knockdown of PCK2 enhanced apoptosis and cell death under glucose deprivation in lung cancer cells with inactivating mutations of the tumor suppressor liver kinase B1 (LKB1), but not in a lung cancer cell line with wild-type LKB1." (PMID 26682254, 2015). "Single-cell analysis and immunostaining revealed expression of PCK2 in macrophages from both lung cancer and normal lung." (PMID 41160607, 2025). "Conversely, PCK2 was shown to be critical for the proliferation of lung cancer cells, kidney renal clear cancer cells and breast cancer cells." (PMID 39193344, 2024). "Taken together, our data show that PCK2-mediated gluconeogenesis promotes tumorigenesis of NSCLC in vivo by protecting lung cancer cells against apoptosis." (PMID 39193344, 2024). "We and others have previously shown that the mitochondrial isoform of phosphoenolpyruvate carboxykinase (PCK2) is the key enzyme in lung cancer cells mediating the conversion of oxaloacetate to PEP in the (truncated) gluconeogenesis pathway." (PMID 38515202, 2024). "Lung cancer cells treated with low-glucose, serum-free media showed upregulation of PCK2 and conversion of stable isotopically labelled lactate along the PCK2 pathway to PEP." (PMID 33540663, 2021). "Inhibition of cancer growth by inhibition of PCK1 or PCK2 has been shown in different tumor models in vivo, including xenografts of lung cancer, prostate cancer and colon cancer." (PMID 33540663, 2021). "In recent years, PCK2 has been abnormally expressed in a variety of cancers, such as liver cancer, colorectal cancer, lung cancer, melanoma and prostate cancer, which is closely related to the occurrence and development of cancer." (PMID 33142842, 2020). "Similar upregulation of PCK2 by low glucoses was also determined in A549 and H23 lung cancer cells, but its interference and inhibition also significantly enhanced their apoptosis induced by glucose deprivation." (PMID 32774674, 2020). "We show that PCK2 expression was decreased by hypoxia in lung cancer cells in vitro, while the opposite was true for glycolysis marker GLUT1." (PMID 32777161, 2020). "Knockdown of PCK2 or addition of the PEPCK inhibitor 3-Mercaptopicolinate (3-MP) to lung cancer cells significantly enhanced glucose depletion-induced apoptosis of these cells." (PMID 29262588, 2017). "Elevated PCK2 has been reported in lung cancer cell lines, non-small cell lung cancer samples, and other types of cancer cells." (PMID 29137367, 2017). "Furthermore, a role of PCK2 in different human macrophage populations in vivo is suggested by its robust expression in macrophages from human lungs and lung cancers." (PMID 41160607, 2025). "The expression of PCK2 in lung cancer cell lines increases in response to low‐glucose conditions." (PMID 35757841, 2023). "Here, we analyzed the expression of GLUT1, the prime glucose transporter, and of PCK1 and PCK2, the cytoplasmic and mitochondrial isoforms of PEPCK, in 450 samples of non‐small cell lung cancer (NSCLC) and in 54 NSCLC metastases using tissue microarrays and whole tumor sections." (PMID 32777161, 2020). "Under low glucose conditions, PCK2 expression is up-regulated in lung cancer cells." (PMID 29262588, 2017). "In this way, oxidative lung cancer cells can convert lactate into PEP via the upregulation of PC and PCK2." (PMID 38731909, 2024). "Here we show considerable heterogeneity of the utilization of gluconeogenesis or glycolysis in human non‐small cell lung cancers (NSCLC) and NSCLC metastases and a localization of PCK2 at tumor margins." (PMID 32777161, 2020).
lung carcinoma (continued). "Previous studies reported that the mitochondrial isoform of PEPCK, PCK2, promotes lactate incorporation into PEP in lung cancer cells enabling cells to survive glucose depletion." (PMID 31388420, 2019). "In isotopic tracer experiments we found that lactate is converted via pyruvate carboxylase and PEPCK (PCK2) and thereby contributes to the pool of PEP in lung cancer cells cultured under low glucose." (PMID 26682254, 2015). "In our study we found that PEPCK (the mitochondrial isoform PCK2) is expressed in lung cancer tissue and lung cancer cells." (PMID 26682254, 2015). "The lack of PCK1 or PCK2 expression in some NSCLCs leads to the question, how lung cancer cells remain viable and maintain anabolic biosynthesis in these tumors, if blood perfusion drops." (PMID 32777161, 2020). "Gluconeogenesis, mediated by phosphoenolpyruvate carboxykinase (PCK2), promotes anabolic metabolism in lung cancer cells in the absence of glucose." (PMID 32777161, 2020). "In lung cancer samples, PCK2 activity is 3 times higher compared to the normal tissues." (PMID 32699530, 2020).
Obesity (21 papers, 2010 to 2025). Accumulation of substantial excess body fat. "It has been found that PCK1 and PCK2 can be used as candidate genes of obesity, which can participate in the synthesis of glycerophosphate and promote the accumulation of fat in human body." (PMID 35681299, 2022).
Hypoglycemia (20 papers, 2004 to 2025). A decreased concentration of glucose in the blood. "It was recently demonstrated that hepatic PCK2 mRNA expression increased following the induction of chronic hypoglycemia in fetal sheep and that this was associated with a decrease in circulating insulin and an increase in plasma cortisol." (PMID 35681299, 2022). "PCK1, PCK2, and FBP1, when deficient, have all been associated with hypoglycemia, and may have been upregulated as a compensatory mechanism to potentially provide needed intermediates within the glycolytic pathway." (PMID 38731997, 2024). "As not all dogs had measurable episodes of hypoglycemia, another albeit highly speculative pathomechanism should be considered: PCK2 acts as a sensor of the citric acid cycle (‘Krebs cycle’) flux by removing oxaloacetate." (PMID 32660061, 2020).
Glucose intolerance (19 papers, 2012 to 2025). Glucose intolerance (GI) can be defined as dysglycemia that comprises both prediabetes and diabetes. "Whole-body PCK2-/- mice display glucose intolerance and reduced insulin secretion in response to glucose and AA." (PMID 35997256, 2022).